NRP1 (neuropilin 1)
Diseases named in the same sentence as NRP1 in open-access papers (continued):
Sharing a sentence is not in itself a finding about the gene and the disease.
glioma (continued). "Hence, NRP1 and NRP2 were identified as candidate special receptor of GDNF in C6 glioma cells and we chose to further investigate NRP1 in this study." (PMID 29088765, 2017). "Our results are the first to our knowledge to demonstrate that in vivo pharmacological inhibition of Nrp1, not just its genetic ablation, results in better outcomes in the glioma disease course." (PMID 26755653, 2016). "Knockdown of either Nrp1 or p130Cas, or alternatively expression of either Nrp1 without its cytoplasmic domain or a non-functional p130Cas mutant, all reduced the GF-induced migration of endothelial cells and glioma cells." (PMID 22948112, 2012). "Interestingly, the hepatocyte growth factor (HGF) has been identified recently as an additional ligand for NRP1, which potentiated HGF/c-Met signalling and promoted glioma progression and pancreatic cancer cell invasion." (PMID 20087344, 2010). "As VEGF165 binds to NRP2, competition between SEMA3B/3G and VEGF165 for binding to NRP2 might exist in gliomas as demonstrated for SEMA3A and NRP1 in ECs." (PMID 18781179, 2008). "Nrp1 is also expressed by other cell types, raising the question of whether the ability of EG00229 to suppress tumor growth is also due to its effects on endothelial cells and/or the glioma tumor cells." (PMID 26755653, 2016). "It has been shown that Nrp1 expression by tumor cells is correlated with the degree of biologic aggression of human gliomas but it is not known whether Nrp1 is also expressed by macrophages within the human tumor microenvironment." (PMID 26755653, 2016). "However, it is not known whether this also occurs in glioma cells, even though Hif1a levels correlate with Nrp1 levels in glioblastoma." (PMID 36203599, 2022). "NRP1 is more highly expressed in human GBM and C6 rat glioma cells than in non-tumoral human brain tissue and primary rat astrocytes." (PMID 37894289, 2023). "We next studied the uptake of CF555-labeled PL3-AgNPs in TNC-C and NRP-1-positive U87-MG glioma cells, NRP-1-positive PPC1 prostate carcinoma cells, and in TNC-C and NRP-1-negative M21 melanoma cells." (PMID 32242067, 2020). "Further, immunofluorescent (IF) staining showed that exogenous GDNF recruited more NRP1 to the cell membrane of C6 glioma cells, whereas the non-GDNF treated cells showed diffused cytoplasmic staining for NRP1." (PMID 29088765, 2017). "For the other studied genes (SEMA3A, B, C, E, F, G, NRP1, NRP2 and SEMA4D), we did not observe statistical difference between low- and high-grade gliomas." (PMID 18781179, 2008). "RT-PCR of 37 glioma specimens, out of which 17 were grade IV GBM tumors, showed that NRP1 mRNA expression is higher in GBM than in non-tumoral tissue and lower-grade gliomas, and glioma patients with NRP1 overexpression (56.8%) showed a poorer prognosis indicated by reduced overall survival." (PMID 37894289, 2023).
melanoma (73 papers, 2012 to 2025). A malignant, usually aggressive tumor composed of atypical, neoplastic melanocytes. "Overexpression of NRP1 is associated with poor prognosis in various cancers including prostate cancer, lung cancer, and melanoma." (PMID 32408477, 2020). "In conclusion, increased NRP1 expression is associated with disease progression and reduced survival in patients with melanoma, and is a promising prognostic molecular marker for this disease." (PMID 25954957, 2015). "A similar process of phenotype switching has been reported in melanoma and implicated in promotion to a metastatic state, providing further evidence of NRP-1 involvement in multiple oncogenic functions." (PMID 26090340, 2015). "CendR receptor NRP-1 is widely expressed in normal tissues and overexpressed in malignant and malignancy-associated cells in a wide range of solid tumors, including prostate, breast, pancreas and hepatocellular carcinoma, melanoma, glioblastoma, and leukemia." (PMID 37111013, 2023). "High numbers of intratumoral Nrp1+ Tregs are associated with poor prognosis and outcomes in melanoma and head and neck squamous cell carcinoma, as they are driving a shift towards an IFNγ-insensitive immunosuppressive phenotype for CD8+ cells that is conducive to tumor growth." (PMID 36203599, 2022). "A similar mechanism has been recently described in murine B16 melanoma cells, where tumor-associated NRP-1 can prevent VEGFR2/VEGF-A internalization and signaling in endothelial cells through a trans complex formation, suppressing tumor initiation and angiogenesis." (PMID 26090340, 2015). "In addition, the present study investigated whether NRP1 expression was associated with 10-year survival in patients with melanoma." (PMID 25954957, 2015). "Another integrin, αvβ5 integrin, is involved in the regulation of neuropilin 1 (NRP-1)-dependent angiogenic pathways in melanoma." (PMID 39866233, 2025). "More recently, a study investigated the role of PlGF NRP-1 in promoting melanoma aggressiveness independently of VEGFR-1." (PMID 38791873, 2024). "Neurolipin1 (NRP1), a prognostic marker for melanoma progression, is activated diffusely across the type 1 melanoma areas." (PMID 38785552, 2024). "Recent studies have shown that blocking integrins like αvβ3 and αvβ5 can reduce melanoma aggressiveness by inhibiting pathways such as neuropilin 1 (NRP-1)-dependent angiogenesis." (PMID 39200315, 2024). "MicroRNA-9 was shown to suppress the growth, migration, and invasion of malignant melanoma cells via targeting neuropilin-1 (NRP1)." (PMID 37190188, 2023). "The ability of NRP1 to promote melanoma invasiveness involves Akt activation through its phosphorylation on T308." (PMID 37894289, 2023). "NRP1 expression is also sufficient to promote melanoma cell invasion accompanied by MMP-2 secretion." (PMID 37894289, 2023). "Intratumoral NRP1+ regulatory T cells were described to correlate with poor prognosis in melanoma and head and neck squamous cell carcinoma, where NRP-1 functioned to maintain Tregs stability." (PMID 36672243, 2023). "This integrin/angiogenesis link in melanomas is important as the αVβ3 inhibition in melanoma cells leads to the NRP-1, a coreceptor of VEGF-A being inhibited, thus reducing the αVβ5/NRP-1 dependent angiogenesis in melanoma." (PMID 34439879, 2021). "Previous studies demonstrated that PDGF-C, a platelet derived growth factor, binds directly with NRP-1 in melanoma cells, while also stimulating extracellular matrix invasion and p130C phosphorylation in melanoma cells lacking PDGFRα." (PMID 33807778, 2021). "In a B16 melanoma model, neuropilin-1 (Nrp1) induced intra-tumoral Treg stability by enhancing quiescence/survival genes, while inhibiting transcriptomic signatures that promote differentiation." (PMID 33532902, 2021). "show, in a mouse model of melanomas, that this infiltration of LTreg through NRP1 induces a decrease of the anti-tumor immune response and an improvement in tumor progression." (PMID 34277411, 2021).
melanoma (continued). "The combined blockade of Galectin-1 and NRP1 in drug-resistant melanoma cells restored BRAF-addiction and sensitivity to therapy." (PMID 32784465, 2020). "We observed that the expression of Galectin-1 (Gal-1), a soluble ligand of Neuropilin-1 (NRP1), is upregulated in melanoma tumor samples and melanoma cells resistant to BRAF-targeted therapy." (PMID 32784465, 2020). "It is also shown that Nrp-1 contributes to intratumoral Treg stability, and the high percentage of Nrp1+ Tregs in tumor environments correlates with poor prognosis in both human melanoma and head and neck squamous cell carcinoma." (PMID 33519807, 2020). "In summary, our work shows that Galectin-1 triggers an autocrine NRP1-dependent pathway in melanoma cells, driving adaptive refractoriness to BRAF inhibitors." (PMID 32784465, 2020). "Here, we found that Gal-1 is largely responsible for NRP1-driven melanoma resistance to therapy and that its targeting with a small molecule inhibitor complemented the effect of NRP1-blockers aimed at resuming drug sensitivity." (PMID 32784465, 2020). "Together these data highlight Gal-1 as a potential mediator of NRP1 autocrine signaling in drug-resistant melanoma cells and tumors." (PMID 32784465, 2020). "In contrast, Gal-1 silencing significantly curbed that NRP1 upregulation observed in PLX-resistant melanoma cells at both the mRNA and protein levels, thus suggesting a positive loop mediated by autocrine ligand production." (PMID 32784465, 2020). "In complementary experiments, both A375 and SK-MEL-28 parental melanoma cells transfected to express exogenous Gal-1 also attained consistent NRP1 and EGFR upregulation." (PMID 32784465, 2020). "In particular, we have previously demonstrated that melanoma cells treated with BRAF inhibitors upregulate the cell surface receptor Neuropilin-1 (NRP1), which elicits an EGFR-dependent mechanism of adaptive resistance to therapy." (PMID 32784465, 2020). "We have previously shown that melanoma cells resistant to BRAF-targeted therapy acquire NRP1 neo-expression, driving an intrinsic mechanism of drug refractoriness." (PMID 32784465, 2020). "In summary, we found that the activation of Galectin-1/NRP1 autocrine signaling is a new mechanism conferring independence from BRAF kinase activity to oncogene-addicted melanoma cells." (PMID 32784465, 2020). "Intriguingly, this adaptive upregulation of Gal-1 expression in drug-resistant melanoma cells paralleled that reported for its receptor NRP1." (PMID 32784465, 2020). "Here, we confirm that Gal-1 controls EGFR upregulation in drug-resistant melanoma cells via a NRP1-dependent mechanism." (PMID 32784465, 2020). "A de novo expression of NRP1 in BRAF-addicted melanoma cells contributes significantly to their development of secondary drug resistance by adapting their gene expression, such as upregulation of EGFR." (PMID 30717262, 2019). "We now report, in both human NSCLC tumours and murine B16F10 melanoma, that Nrp-1 delineates a particular subset of CD8+ TIL, enriched with tumour antigen-specific T lymphocytes, and also expressing high levels of the PD-1 inhibitory receptor." (PMID 31350404, 2019). "Next, we analysed the cytotoxic activity of CD8+ TIL toward autologous melanoma cells in the absence or presence of neutralising anti-Nrp-1 and/or anti-PD-1 mAb, with an isotype-matched mAb as negative control." (PMID 31350404, 2019). "In vivo, Nrp-1+PD-1hi CD8+ tumour-infiltrating lymphocytes (TIL) in B16F10 melanoma are enriched for tumour-reactive T cells exhibiting an exhausted state, expressing Tim-3, LAG-3 and CTLA-4 inhibitory receptors." (PMID 31350404, 2019). "miR338 was found to hinder NRP1 expression in melanoma cells, but its levels were downregulated in response to targeted therapy leading to the onset of drug resistance." (PMID 31027288, 2019).
melanoma (continued). "Antibody-mediated blockade of sema4A or genetic deletion of Nrp1 from these Treg populations using FOXP3-Cre resulted in enhanced anti-tumoral immunity in melanoma mouse models." (PMID 32914058, 2018). "Evidence has shown that when integrin αvβ5 was inhibited, NRP-1 as a co-receptor of VEGF-A was also blocked, and thus the NRP-1-dependent angiogenesis and aggressiveness of melanoma was also reduced." (PMID 29703238, 2018). "Most data indicate that it lacks a defined signaling activity, but recent evidence obtained in melanoma cells has suggested that NRP1 is able to activate VEGF-mediated signal transduction pathways also independently of VEGFR-2 expression." (PMID 29535768, 2018). "It has also been shown in a murine melanoma model that Nrp1 expressing Tregs are attracted to tumors via the tumor’s secretion of VEGF, which is abrogated by the inhibition of Nrp1 signaling." (PMID 32914058, 2018). "Expression of NRP-1 in melanoma cells correlates with tumour cell invasive behaviour and formation of tube-like structures resembling vascular networks (vasculogenic mimicry)." (PMID 28977999, 2017). "Our data indicate that the highly aggressive phenotype displayed by NRP-1 proficient melanoma cells is sustained, at least in part, by a PDGF-C/NRP-1 autocrine loop." (PMID 28977999, 2017). "PDGF-C/NRP-1 autocrine loop activity was also explored in two human melanoma cell lines derived from the same patient: one originated from the primary tumour (WM115) and the other from a lymph-node metastasis (WM266-4)." (PMID 28977999, 2017). "The αvβ5 integrin expressed in neuropilin 1-positive melanoma cells, which are highly aggressive cells, has been found to be responsible for vasculogenesis mimicry in melanoma." (PMID 26747273, 2016). "Nrp-1 immunohistochemical staining demonstrated that the anti-Nrp-1 antibody clearly decreased Nrp-1 expression in melanoma tumor tissue." (PMID 27075020, 2016). "NRP1 is frequently overexpressed in several tumor types including carcinomas (e.g., prostate, breast, colon, kidney, pancreas), melanoma, glioblastoma and others, generally correlating with aggressive clinical tumor behavior and poor prognosis." (PMID 27863391, 2016). "Melanomas which express NRP-1 become more aggressive due to the activation of αV integrin, a marker molecule in the conversion of melanoma cells to a metastatic phenotype." (PMID 26558271, 2015). "The results of a recent study add to the evidence suggesting that NRP1 expression promotes invasiveness of melanoma cells through VEGFR2-dependent and -independent mechanisms." (PMID 25954957, 2015). "This review is focused on the role of NRP-1 in melanoma aggressiveness and on the evidence supporting its use as target of therapies for metastatic melanoma." (PMID 26090340, 2015). "High expression of NRP1 was detected in 47% of melanoma specimens at AJCC stage I compared with 60–69% of melanoma specimens at AJCC II–IV (P=0.0005)." (PMID 25954957, 2015). "In order to investigate whether NRP1 expression is associated with 5-year survival of patients with melanoma at specific stages of the disease, the patient cohort was divided into those with primary melanoma and those with metastatic melanoma, and patient survival in each group was analyzed." (PMID 25954957, 2015). "The correlation of NRP1 expression with melanoma progression, and its prognostic value in patients with melanoma was examined." (PMID 25954957, 2015). "It has been recently demonstrated that NRP-1 expression in melanoma cells increases their aggressiveness and ability to form tubule-like structures." (PMID 26090340, 2015). "In this same study, it was shown that αVβ3 integrin promoted ECM invasion in the presence of VEGFR-2 in NRP-1-positive melanoma cells." (PMID 26558271, 2015). "NRP-1 is involved in all these biological processes, being expressed in endothelial, highly aggressive melanoma and immune cells." (PMID 26090340, 2015).
melanoma (continued). "Kruskal-Wallis test on the NRP1 scoring pattern in the melanoma samples revealed that NRP1 expression increased significantly from AJCC I (median 4) to AJCC II–IV (median 8; (P=0.007)." (PMID 25954957, 2015). "NRP-1 is also expressed in a variety of cancers (prostate, lung, pancreatic, or colon carcinoma, melanoma, astrocytoma, glioblastoma, and neuroblastoma), suggesting a critical role in tumor progression." (PMID 26090340, 2015). "Multivariate Cox regression analyses indicated that NRP1 is an independent prognostic marker for melanoma." (PMID 25954957, 2015). "The results showed that in 365 melanoma samples, melanomas with high NRP1 expression also exhibited a significantly higher percentage of high MMP2 staining." (PMID 25954957, 2015). "The results showed that NRP1 expression was significantly reduced in common nevi and dysplastic nevi, compared with primary melanoma and metastatic melanoma." (PMID 25954957, 2015). "In the present study, NRP1 expression was examined in 460 cases of melanocytic lesions (28 common nevi, 51 dysplastic nevi, 250 primary melanoma and 131 metastatic melanoma) at different stages, using a tissue microarray." (PMID 25954957, 2015). "In conclusion, the current study demonstrated that NRP1 expression is significantly correlated with the progression of human melanoma." (PMID 25954957, 2015). "As NRP1 expression was correlated with melanoma progression, the correlation between NRP1 expression and various clinicopathological characteristics was also investigated." (PMID 25954957, 2015). "Neuropilin-1 is expressed in various tumor cells such as breast, prostate, lung, melanoma cells and acute myeloid leukemia." (PMID 23563900, 2013). "While cilengitide showed minimal clinical efficacy as a single-agent therapy in melanoma, it has been demonstrated to reduce the invasiveness and vasculogenic mimicry of neuropilin-1(NRP-1)-expressing melanoma cells by inhibiting αvβ5 integrin and αvβ5 integrin/NRP-1/VEGF-A signaling." (PMID 39195226, 2024). "In melanoma cells, NRP1 expression promotes invasiveness partially through VEGFR-2." (PMID 37894289, 2023). "Interestingly, Nrp1 expression in intratumoral Tregs appeared to correlate with poor prognosis in both melanoma and HNSCC." (PMID 35474948, 2022). "Nrp1 expression in intratumoral Tregs appeared to correlate with poor prognosis in melanoma." (PMID 35474948, 2022). "Decreases melanoma cells proliferation, migration and invasion of through targeting NRP1." (PMID 33968718, 2021). "Thus, Galectin-1/NRP1 signaling represents a druggable mechanism controlling adaptive resistance to therapy in melanoma cells." (PMID 32784465, 2020). "Importantly, NRP1 involvement in Gal-1-driven resistance to therapy in melanoma cells is indicated by different lines of evidence in our study." (PMID 32784465, 2020). "Therefore, we aimed to identify the alternative autocrine ligands potentially triggering NRP1-dependent resistance to BRAF-targeted therapy in melanoma." (PMID 32784465, 2020). "Notably, here we confirmed that Gal-1 controls p27 levels in PLX-resistant melanoma cells, consistent with its role as an autocrine NRP1 activator." (PMID 32784465, 2020). "Thus, Gal-1 autocrine signaling via NRP1 represents a druggable mechanism mediating melanoma cell resistance to BRAF inhibitors." (PMID 32784465, 2020). "Since both Gal-1 and its receptor NRP1 were upregulated in melanoma cells upon drug resistance onset, we asked whether their relative expression was linked in a signaling circuit." (PMID 32784465, 2020). "Finally, the combined treatment with a Gal-1 inhibitor and a NRP1 blocking drug enabled resistant melanoma cell resensitization to BRAF-targeted therapy." (PMID 32784465, 2020). "Likewise, NRP1 was reported to mitigate migration of melanoma cells (i.e., M14, GR-Mel) though VEGF-A-induced activation of VEGFR2, or independently in response to PLGF, even in the absence of its high affinity receptor, VEFGR1." (PMID 33121034, 2020).